PHLDA2 (pleckstrin homology like domain family A member 2)
Diseases named in the same sentence as PHLDA2 in open-access papers (continued):
Sharing a sentence is not in itself a finding about the gene and the disease.
melanoma (2 papers, 2013 to 2025). A malignant, usually aggressive tumor composed of atypical, neoplastic melanocytes. "We observed that AGRN is primarily secreted by C2 PHLDA2+ Melanoma cells subgroup and C4 PCLAF+ Melanoma cells subtype, with its main target cells (receptors) were the majority of melanoma cells." (PMID 39781353, 2025). "We found that TGFb can be secreted by immune cells (T_NK cells, B_Plasma cells, Myeloid cells), ECs, Fibroblasts, C2 PHLDA2+ Melanoma cells, C4 PCLAF+ Melanoma cells and C5 CD74+ Melanoma cells, and targeting C2 PHLDA2+ Melanoma cells and C4 PCLAF+ Melanoma cells." (PMID 39781353, 2025). "Besides, TNFb is predominantly secreted by various immune cells, ECs, Fibroblasts and a subset of melanoma cells, and its target cells were C2 PHLDA2+ Melanoma cells and C4 PCLAF+ Melanoma cells." (PMID 39781353, 2025). "As could be seen from the figure, C2 PHLDA2+ Melanoma cells and C4 PCLAF+ Melanoma cells had the highest expression on the ARGN signaling pathway." (PMID 39781353, 2025). "Additionally, we found that the TGFb signaling pathway only targets the C4 PCLAF+ Melanoma cells and C2 PHLDA2+ Melanoma cells subgroup, which suggests that this pathway plays an important role in the C4 subgroup." (PMID 39781353, 2025). "Specifically, FLRT2 was downregulated while MAD1L1, PHLDA2, PLAT, CC2D1B, CDKN2A and RUNX3 were upregulated in both melanoma and in Group 2 and Group 3 SFs." (PMID 23371019, 2013). "We characterized melanoma cells and conducted dimensionality reduction clustering, revealing six distinct cell subgroups: C0 TRPM1+ Melanoma cells, C1 PIR+ Melanoma cells, C2 PHLDA2+ Melanoma cells, C3 ID2+ Melanoma cells, C4 PCLAF+ Melanoma cells, and C5 CD74+ Melanoma cells." (PMID 39781353, 2025).
ovarian carcinoma (2 papers, 2022 to 2024). A malignant neoplasm originating from the surface ovarian epithelium. "Moreover, any significant variation (high or low) in PHLDA2 expression can be used as a reliable predictive indicator of poor prognosis in ovarian cancer patients." (PMID 38921000, 2024). "Among the PHLDA family, PHLDA1 might serve as a therapeutic target for several cancers, such as colon, ovarian, and pancreatic cancer, while PHLDA2 might be used as a therapeutic target for esophageal, kidney, and ovarian cancer." (PMID 38921000, 2024).
pancreatic cancers (2 papers, 2022 to 2024). "Brain, esophagus, liver, and pancreatic cancers were positively associated with PHLDA2 genes, and 188 of these genes were common in all cancers." (PMID 38921000, 2024). "The oncogenic significance of PHLDA2 in ovarian and pancreatic cancer, however, revealed that other factors should be considered when determining the prognosis of cancer." (PMID 38921000, 2024). "The expression level of genes TNNT1, KCNN4, SH2D3A, and PHLDA2 was significantly different between the 179 pancreatic tumors and 171 normal tissue samples." (PMID 35712127, 2022). "Analysis of the expression level of the hub genes indicated that the genes TNNT1, KCNN4, SH2D3A, and PHLDA2 were differentially expressed between 179 pancreatic tumors and 171 normal tissue samples." (PMID 35712127, 2022). "PHLDA2 has an oncogenic role in brain, colon, esophageal, ovarian, lung, and pancreatic cancers." (PMID 38921000, 2024).
placental insufficiency (2 papers, 2012 to 2014). Failure of the placenta to deliver an adequate supply of nutrients and oxygen to the fetus. "We have previously reported a direct causative effect between high PHLDA2 and late onset growth restriction in an animal model, which we attributed to placental insufficiency." (PMID 22100507, 2012). "We furthermore show that this Phlda2-driven growth restriction is asymmetrical, with a relative sparing of the brain, followed by rapid catch-up growth after birth, classic features of placental insufficiency." (PMID 25085993, 2014).
preeclampsia (2 papers, 2024 to 2025). Preeclampsia is a hypertensive disorder of pregnancy that is characterized by new-onset hypertension with proteinuria presenting after 20 weeks of gestation, and depending on mild or severe forms may initially present with severe headache, visual disturbances, and hyperreflexia. "Furthermore, dysregulated expressions of several imprinted genes (e.g., Igf2, Phlda2, H19 and Gab1) in the placenta have been implicated in various pregnancy complications, including preeclampsia, gestational diabetes and FGR." (PMID 40550626, 2025). "Dysregulation of imprinted genes, including Igf2, Phlda2, H19 and Gab1 has been observed in placentas affected by pregnancy complications including preeclampsia, gestational diabetes and FGR." (PMID 40550626, 2025).
behavioural disorders (1 paper, 2021). "Given the prevalence of elevated PHLDA2 in FGR infants, this alteration may contribute to the behavioural disorders observed in this high-risk population." (PMID 34100083, 2021).
brain tumors (1 paper, 2005). "Somatostatin has shown a wide range of growth inhibitory activity in vitro and in vivo.PHLDA2 (TSSC3) is an imprinted gene homologous to the murineTDAG51 apoptosis-related gene, and may be involved in human brain tumors." (PMID 15691381, 2005).
COVID-19 (1 paper, 2023). A disease caused by infection with severe acute respiratory syndrome coronavirus 2. "For instance, IL1B, NFKB1, NLRP3, PYCARD, and CASP1 are listed in the COVID-19 Disease Map, while there are molecules absent from it, including CCL3, 3L1, 4L2, CXCL1, 2, 3, 5, 16, TNFAIP6, C15orf48, TMEM176A/B, NFE2, PADI4, RAB20, ETS2, PHLDA2, FOLR3, and HP." (PMID 37719701, 2023).
depression (1 paper, 2016). "In an initial pilot study, expression of the imprinted genes PEG3, PEG10, PHLDA2 and CDKN1C was analysed in a cohort of placentas (n = 75), which included a subset of women (n = 7) who had diagnosed depression during pregnancy." (PMID 27523184, 2016).
gastric cancer (1 paper, 2024). A primary or metastatic malignant neoplasm involving the stomach. "In gastric cancer, the HGF (hepatocyte growth factor)-mediated overexpression of PHLDA2 is linked to apoptosis." (PMID 38921000, 2024).
jejunal cancer (1 paper, 2022). A malignant neoplasm involving the jejunum. "We found that some upregulated DEGs in GC malignant cells such as HSPB1, PHLDA2, DNAJB1 have the decreasing expression tendency in malignant cells from GC, duodenal caners, jejunal cancers to CRC." (PMID 36104333, 2022).
meningioma (1 paper, 2018). A generally slow growing tumor attached to the dura mater. "Six of these genes were usually underexpressed (RUNDC3B, ANGPT2, PHLDA2, CAV2, EDNRA, and SCG2) in non-aggressive/non-recurrent tumors and overexpressed in more aggressive/recurrent meningiomas." (PMID 29662628, 2018).
mood disorder (1 paper, 2018). A cognitive disorder a disturbance in which the person's mood is hypothesized to be the main underlying feature. "Elevated placental PHLDA2 is a common findings in foetal growth restriction, which is associated with mood disorders in human pregnancies." (PMID 30063711, 2018).
pleural mesothelioma (1 paper, 2021). A neoplasm that arises from the mesothelial cells of the pleura. "We collected the methylation profile of pleural mesothelioma, and found 8 novel interactors to be hypomethylated in pleural mesothelioma versus non-tumor pleural tissue, namely, ACVR1B, IL6, MGMT, NRG1, OAT, PHLDA2, PLAUR and TNC." (PMID 33916178, 2021).
tumor (23 papers, 2010 to 2025). "We also found that PHLDA2 was significantly associated with tumor stemness and involved in regulating drug resistance." (PMID 38827322, 2024). "Moreover, the tumor-suppressive role of PHLDA2 has been implicated in different mouse tumor models, including the genetically well-defined lymphoma model and the pharmacologically induced liver cancer model." (PMID 39210510, 2024). "In summary, PHLDA2 exhibits a significant association with tumor stemness." (PMID 38827322, 2024). "None of the antitumor agents in the CCLE-GDSC dataset had their response associated with PHLDA2 copy number, suggesting that the associations of drug response with expression of this gene in tumor cells may be influenced by its transcriptional regulation rather than by copy number changes." (PMID 36461044, 2022). "By using both immunodeficient and immunocompetent mouse tumor models, we found that PHLDA2 is crucial for tumor suppression by inducing ferroptosis naturally in vivo without any drug treatment from common ferroptosis inducers." (PMID 39210510, 2024). "To determine the expression of PHLDA2 in both tumor and normal tissues, we conducted a query of the TIMER database." (PMID 38827322, 2024). "So, we infer that the upregulation of PHLDA2 can increase genomic instability, activate oncogenes, or deactivate tumor suppressor genes, thereby promoting tumor development." (PMID 38827322, 2024). "PHLDA2 enhances pancreatic ductal adenocarcinoma tumor growth, and its downregulation is seen in some human cancers, including osteosarcoma; hence, it has tumor-suppressing properties." (PMID 38921000, 2024). "It showed that PHLDA2 was highly expressed in human HCC tissues compared with adjacent tumor tissues." (PMID 37952028, 2023). "Tumour-suppressing STF cDNA 3 (TSSC3) (also known as Pleckstrin homology-like domain family A member 2/PHLDA2) was expressed in the cytoplasm of cytotrophoblasts (CT) of all cases of PMs (15/15, 100%) and NMAs (17/17, 100%)." (PMID 37298606, 2023). "The results showed that there were significant correlations between a high frequency of PHLDA2 mRNA mutations and two clinicopathological features of PAAD: the invasion of surrounding tissues and tumor sites (p < 0.05)." (PMID 36142223, 2022). "High levels of the imprinted gene pleckstrin homology like domain family A member 2 (PHLDA2) correlate with tumor progression in several malignancies." (PMID 32385195, 2020). "Taken together, these results suggest that downregulation of PHLDA2 inhibits tumor growth and PI3K, thereby promoting autophagy and inhibiting EMT, in part through the PI3K/AKT/mTOR and PI3K/AKT/GSK-3β signaling pathways." (PMID 32385195, 2020). "The potential tumor suppressor role of PHLDA2 with downregulated protein expression has been explored in several human cancers." (PMID 31058093, 2019). "Pleckstrin homology-like domain family A member 2 (PHLDA2) is located within the tumor suppressor region of 11p15, and its expression is suppressed in several malignant tumor types." (PMID 29861842, 2018). "The function of PHLDA2 in cancers is still largely unclear albeit it is one of several genes in the imprinted gene domain of 11p15.5 which is considered to be an important tumor suppressor gene region." (PMID 29861842, 2018). "Within the top 20 genes ranked by Notch pathway-guided COCA, there are several genes related to differentiation (Tdgf1, Egr1 and Lefty1), cell growth (Ddit4, Hk2, Phlda2, Egln3 and Igfbp1) and tumor/cancer development (Afp, Sfrp2, Egr1, Hk2 and Phlda2)." (PMID 20353603, 2010). "In addition, over-expression of PHLDA2 has been reported to promote tumor development in multiple cancers." (PMID 39033192, 2024).
tumor (continued). "However, the methylation level of the PHLDA2 promoter in paracancerous tissues was significantly higher than that in tumor tissues (p = 3.170 × 10−2)." (PMID 36142223, 2022). "In conclusion, we demonstrated that PHLDA2 is a CRC tumor promoter." (PMID 32385195, 2020). "Interestingly, a significantly lower expression of PHLDA2 was observed in tumor samples with a mean value of 0.29 compared to paired normal tissue." (PMID 31058093, 2019). "In all, PHLDA2 may play an essential role in tumor stemness maintenance." (PMID 38827322, 2024). "However, PHLDA2 could also suppress tumor development by triggering a distinct ferroptosis response, suggesting complex roles of PHLDA2 in tumorigenesis." (PMID 39033192, 2024). "Importantly, low levels of PHLDA2 inhibited tumor growth in vivo." (PMID 32385195, 2020). "Conversely, the genes FTH1, SQSTM1, HSPA6, TSPYL2, PHLDA2, ITGAX, and DNAJA4 are expected to act as versatile protein regulators, potentially suppressing tumor cell genetic instability and promoting autophagy, apoptosis, and other forms of cell death." (PMID 40986633, 2025). "Thus, whether PHLDA2 functions as an oncogene or a tumor suppressor depends on the type of cancer." (PMID 39033192, 2024). "However, in certain cancers, PHLDA2 could also act as a tumor suppressor." (PMID 39033192, 2024). "Thus, targeting PHLDA2 could potentially impede the recruitment of TAMs, reprogram the polarization of TAMs, and suppress Tregs-induced immune tolerance to enhance anti-tumor immunity, thereby reshaping the tumor immune microenvironment." (PMID 38827322, 2024). "Unsurprisingly, a notable pattern of elevated PHLDA1, PHLDA2 and PHLDA3 expression in tumor tissues was observed in both GSE40435 and GSE53757 (all p < 0.05)." (PMID 39033192, 2024). "The results show that the roles of PHLDA1 and PHLDA2 in PAAD immune regulation were opposite, which indicated that the roles of the PHLDA family members in PAAD tumor immune regulation are diverse and complex." (PMID 36142223, 2022). "We found that inhibition of PHLDA2 reduced the proliferation of HCT116 and SW480 cells in this mouse tumor model and inhibited the expression of KI67 protein." (PMID 32385195, 2020). "Since PHLDA2 mediates AKT inhibition, we further analyzed the functional role of PHLDA2 in tumor growth of NSCLC cells." (PMID 29861842, 2018). "Tumor-suppressing STF cDNA 3 (TSSC3), also known as PHLDA2, IPL or BWR1C, is located on chromosome 11p15, a tumor suppressor region, and is the first identified apoptosis-related imprinted gene." (PMID 30092789, 2018). "In the high miR-214 subgroup, 12 tumor samples showed weaker or a lack of PHLDA2 expression (12/16), and significant negative relativity with miR-214 and PHLDA2 was observed (r = −0.802)." (PMID 31058093, 2019). "In summary, enrichment analysis results suggested that PHLDA2 may play a role in promoting tumor development by angiogenesis and EMT, and PHLDA2 may be involved in the regulation of the WNT signaling pathway,PI3K-AKT signaling pathway, TNF signaling pathway, and TGF-β signaling pathway." (PMID 38827322, 2024).
tumor (continued). "In contrast, Hes1, a Notch target gene normally associated with stemness and absorptive cell differentiation, and Phlda2, a growth restriction gene in development and a tumor suppressor, were upregulated in APC and AOM/DSS tumor cells, but not in squamous cells." (PMID 35600339, 2022).
cancer (18 papers, 2010 to 2024). A tumor composed of atypical neoplastic, often pleomorphic cells that invade other tissues. "An immunosuppressive microenvironment featured by high infiltrates of Tregs and cancer-associated fibroblasts, was observed in ccRCC with higher PHLDA2 expression." (PMID 39033192, 2024). "In comparison to PHLDA1, fewer genes associated positively with PHLDA2 in each type of cancer, and 188 genes (referred to as the “PHLDA2-correlated gene cluster” above) were common for all four tumors studied." (PMID 38921000, 2024). "Additionally, a limited number of 12 genes were found to be negatively linked with PHLDA2 in all cancers investigated." (PMID 38921000, 2024). "PHLDA2 is an imprinted gene associated with several cancers." (PMID 32385195, 2020). "Despite all of these approaches, there is still little research on PHLDA2 expression in cancer and its relevance to clinical outcomes." (PMID 38921000, 2024). "So far, PHLDA family members, including PHLDA1, PHLDA2, PHLDA3, have gained more attention due to their association with various cancers." (PMID 39033192, 2024). "This study has discovered that PHLDA2 induces alterations in the immune microenvironment, exhibits a correlation with cancer stemness and facilitates the development of treatment tolerance." (PMID 38827322, 2024). "Further research should be conducted to investigate the predictive role of PHLDA2 for therapeutic efficacy of ICI monotherapy or ICI plus anti-angiogenic agent combination therapy among other cancer types." (PMID 39033192, 2024). "Since these pleckstrins are highly expressed in some cancers, the R2 genomics platform was utilized to find genes associated with PHLDA1, PHLDA2, and PHLDA3." (PMID 38921000, 2024). "Our results expand the dimension of precision medicine, and further studies should be conducted to explore the potential role of PHLDA2 as a predictor biomarker for response of ICI or ICI-based combination therapy among other types of cancer." (PMID 39033192, 2024). "We conducted a comprehensive analysis using the R2 platform to detect genes associated with PHLDA1, PHLDA2, and PHLDA3 expression in particular cancers." (PMID 38921000, 2024). "Conversely, single depletion of endogenous PHLDA1 or PHLDA2 by their specific siRNAs only slightly enhanced AKT activity in cancer cells, whereas their co-depletion resulted in a much greater increase in AKT activity." (PMID 35831322, 2022). "Lastly, we demonstrate that PHLDA2 expression has functional impact in EGFR/ErbB2-driven cancer cells and can modulate the efficacy of molecularly targeted therapy." (PMID 29861842, 2018). "PHLDA2 is an apoptosis-related gene that maps to a paternally-imprinted region involved in cancer development." (PMID 20064253, 2010). "Previous studies have reported that PHLDA family members play vital roles in cancer metabolism, suggesting that in ccRCC, PHLDA2 may also shape an immunosuppressive microenvironment by regulating metabolism." (PMID 39033192, 2024). "The analysis of the PrognoScan database showed PHLDA2 expression in patients with several cancers." (PMID 38921000, 2024). "In contrast to PHLDA2, we discovered 85 genes (referred to as the “PHLDA3-centered positive cluster”) that were positively linked with PHLDA3 and were present in every component of cancer set A." (PMID 38921000, 2024). "Our study of the underlying mechanism of cancer prognosis concerning pleckstrin expression may be aided by the finding that the patterns of PHLDA1, PHLDA2, and PHLDA3 co-expression regulated the clinical outcomes of individuals with certain types of cancer." (PMID 38921000, 2024). "PHLDA2 was elevated in a variety of cancers; however, it was downregulated in sarcoma cancer." (PMID 38921000, 2024).